BANCR (BRAF-activated non-protein coding RNA)
Synonyms: LINC00586
Gene: Long non-coding RNA gene on chromosome 9 (69,296,671 to 69,311,111, reverse strand). Ensembl gene ENSG00000278910.
Diseases named in the same sentence as BANCR in open-access papers:
BANCR is named in the same sentence as 44 diseases in open-access papers, as found by Europe PMC text mining. Sharing a sentence is not in itself a finding about the gene and the disease. The quoted sentences say what the papers report.
melanoma (54 papers, 2013 to 2025). A malignant, usually aggressive tumor composed of atypical, neoplastic melanocytes. "Fifty nontargeting sgRNAs were incorporated as negative controls as well as positive controls against five known melanoma-associated lncRNAs (BANCR, CDKN2B-AS1, HOTAIR, MALAT1, and SAMMSON)." (PMID 40552742, 2025). "Mechanistically, BANCR acts as a competing endogenous RNA (ceRNA) for miR-204 and is associated with poor prognosis in melanoma." (PMID 35159386, 2022). "Downregulation of BANCR in BRAF-mutated melanoma cell lines alters the expression of 88 genes, and most of the repressed genes have been involved in melanoma motility." (PMID 34638331, 2021). "A critical role of BANCR in progression and metastasis of malignant melanoma and bronchial carcinoma is linked to the MAPK pathway." (PMID 31547203, 2019). "BANCR was dysregulated in various cancers including melanoma, colorectal cancer, retinoblastoma, lung carcinoma and hepatocellular carcinoma, and increased BANCR expression cause poor prognosis and shorter survival rate of cancer patients." (PMID 29212285, 2017). "For example, the lncRNA BANCR was found as a recurrently overexpressed transcript in BRAFV600E-mutant human melanoma, which is the most activating mutation in melanoma, with a potential role in regulating cell migration." (PMID 25116943, 2014). "BANCR overexpression is observed in melanoma cells and is significantly associated with metastasis." (PMID 27686732, 2016). "This study aimed to investigate whether BRAF-activated non-coding RNA (BANCR), a novel and potential regulator of melanoma cell, participates in the proliferation of malignant melanoma and elucidate the underlying mechanism in this process." (PMID 24967732, 2014). "BRAF activated non-coding RNA (BANCR), a 693-nt lncRNA encoded on human chromosome 9, has been found to be aberrant expressed in quite a few cancers, such as colorectal cancer, retinoblastoma, melanoma, papillary thyroid carcinoma, lung carcinoma,gastric cancer and hepatocellular carcinoma." (PMID 27514530, 2016). "Moreover, we found BANCR is associated with poor prognosis of patients with malignant melanoma." (PMID 24967732, 2014). "They found that knockdown of BANCR decreases proliferation across three independent melanoma cell lines." (PMID 41463281, 2025). "Restoration of CXCL11 expression rescues the migratory capacity of the cells, suggesting that BANCR indirectly regulates melanoma cell migration through CXCL11." (PMID 41463281, 2025). "In a subsequent study using shRNA, researchers investigated the effect of BANCR on melanoma cell proliferation." (PMID 41463281, 2025). "BANCR, a 693 bp RNA located on chromosome 9, was initially identified in melanoma in 2012 through RNA sequencing screening for transcripts influenced by the oncogene BRAFV600E." (PMID 39894218, 2025). "BANCR regulates melanoma cell migration, and the knockdown of BANCR inhibits melanoma cell migration." (PMID 39408810, 2024). "Other lncRNAs influencing epithelial-mesenchymal transition (EMT) include BRAF-activated lncRNA (BANCR) which is overexpressed in melanoma and thus plays a potential functional role in melanoma cell migration." (PMID 38601651, 2024). "Several lncRNAs, such as HOTAIR, MALAT1, and BANCR have been reported to be dysregulated in melanoma." (PMID 38561355, 2024). "In this 2017 study, researchers discovered that microRNA-204 (miR-204), a suppressor of melanoma growth, is possibly a direct target of BANCR." (PMID 37629553, 2023). "It has been shown that BANCR promotes melanoma by the activation of ERK1/2 and JNK kinases, which results in shorter overall survival of melanoma patients." (PMID 37325482, 2023). "One such ncRNA is the BANCR, which was found to be highly expressed in melanoma tissues compared to melanocytic nevi and human melanocytes." (PMID 37629553, 2023).
melanoma (continued). "The observed associations between expression levels of BANCR and BRAF mutation in the melanoma and papillary thyroid cancer implies the regulatory role of this gene expression of BANCR." (PMID 34409032, 2021). "BANCR has been up-regulated in numerous types of cancers such as endometrial, gastric, breast, melanoma, and retinoblastoma." (PMID 34409032, 2021). "The expression of BANCR has been positively correlated with melanoma stage, and patients with high BANCR expression are characterized with lower OS." (PMID 34638331, 2021). "One of them, the C-X-C motif chemokine ligand 11 (CXCL11), is able to reverse melanoma cells motility, when upregulated in BANCR-depleted cells." (PMID 34638331, 2021). "The observed up-regulation of BANCR in melanoma, has been a starting point for subsequent expression studies in diverse types of cancers." (PMID 34409032, 2021). "The infiltration of melanoma cells can be inhibited in vitro and in vivo by knocking out BANCR in sk-mel-5 cells." (PMID 31844121, 2019). "On one hand, BANCR knockdown inhibited the malignant progression of melanoma, colorectal cancer and osteosarcoma." (PMID 28009984, 2017). "Flockhart and his colleagues firstly observed that BANCR was overexpressed in melanoma cells and played a critical role in melanoma cell migration." (PMID 28969673, 2017). "BANCR and SLNCR1 expression levels in primary melanoma samples were associated with lower survival rates." (PMID 28415644, 2017). "Elevated expression of BANCR promoted the melanoma cell proliferation by activating ERK1/2 and JNK pathway." (PMID 29383102, 2017). "In fact, BANCR were shown to play a critical role in the proliferation and metastasis of malignant melanoma and lung cancer." (PMID 28938549, 2017). "Depletion experiments demonstrated that BANCR has a regulatory function in melanoma cell migration, whereas its absence significantly decreases cellular migration." (PMID 28350340, 2017). "BRAF-activated BANCR has been shown to promote cell migration and proliferation in melanoma and lung carcinoma via the MAPK signaling pathway." (PMID 27462868, 2017). "For example, BANCR is involved in malignant melanoma and lung cancer; thus, researchers explored its role in retinoblastoma." (PMID 27043545, 2016). "BANCR promotes cell proliferation by regulating MAPK pathway activation in both malignant melanoma and lung carcinoma." (PMID 27514530, 2016). "BANCR levels in human malignant melanoma tissues increased with advanced tumor stages, and the knockdown of BANCR suppressed melanoma cell proliferation and migration through MAPK pathway." (PMID 26758762, 2016). "BANCR, an lncRNA originally identified in melanoma cells 693 bp in length, is highly expressed in melanoma cells and is crucial for melanoma cell migration." (PMID 25928067, 2015). "Taken together, our finding provided a novel interpretation for the mechanism of BANCR-regulated proliferation in malignant melanoma." (PMID 24967732, 2014). "Taken together, we confirmed the abnormal upregulation of a novel lncRNA, BANCR, in human malignant melanoma." (PMID 24967732, 2014). "Because of the different expression patterns for BANCR in NSCLC and melanomas, we investigated the mechanisms controlling tissue-specific expression of BANCR." (PMID 24655544, 2014). "Our results showed that BANCR was highly expressed in human malignant melanoma cell lines and tissues, and increased with tumor stages." (PMID 24967732, 2014). "We found that BANCR was abnormally overexpressed in human malignant melanoma cell lines and tissues, and increased with tumor stages by quantitative PCR." (PMID 24967732, 2014). "Expression of BANCR in a total of 103 human tissue specimens of malignant melanoma with various cancer stages and melanoma cell lines was detected using SYBR green quantitative PCR analysis." (PMID 24967732, 2014).
melanoma (continued). "Being overexpressed in melanoma, the oncogenic BRAF-induced BANCR can regulate a set of genes involved in cell migration and is required for full migratory capacity of melanoma cells." (PMID 24967732, 2014). "In the current study, we confirmed the contribution of BANCR in the proliferation of melanoma cells and the potential mechanisms." (PMID 24967732, 2014). "BRAF-activated lncRNA (BANCR) is overexpressed in melanoma and has a potential functional role in melanoma cell migration." (PMID 25013510, 2014). "In previous studies, shRNA-mediated knockdown of BANCR in melanoma cells was revealed to alter the expression levels of 88 genes, several of which are involved in cell migration and chemotaxis." (PMID 25289082, 2014). "Our data demonstrated that BANCR can promote melanoma proliferation via activating ERK1/2 and JNK MAPK pathway both in vitro and in vivo." (PMID 24967732, 2014). "In the present study, we confirmed the role of BANCR in the proliferation of malignant melanoma, and aimed to elucidate the contribution of MAPK pathway in this process." (PMID 24967732, 2014). "BANCR was the mutant BRAFV600E-activated long non-coding RNA identified from samples from BRAF-mutant human melanomas." (PMID 24967732, 2014). "Taken together, it indicated that BANCR regulated cell proliferation, and BANCR depletion impaired proliferation of melanoma cells with high expression of BANCR." (PMID 24967732, 2014). "A significantly increased level of BANCR was seen in patients with malignant melanoma (P = 0.007), compared with the levels detected in age/gender-matched controls with melanocytic nevus." (PMID 24967732, 2014). "For example, BANCR was found overexpressed in melanoma and required for full migratory capacity of melanoma cells by upregulating CXCL11, an important gene involved in cell migration." (PMID 25435812, 2014). "The shRNA-mediated knockdown of BANCR in melanoma cells changes the expression levels of 88 genes, a number of which are involved in cell migration and chemotaxis." (PMID 25013510, 2014). "For example, the first three exons (out of four, i.e. ∼86% of the sequence) of the mature transcript of BANCR, which is involved in melanoma cell migration, are derived from a MER41 long terminal repeat/endogenous retrovirus (LTR/ERV) element." (PMID 23637635, 2013). "The newly identified lncRNA BANCR was found overexpressed in melanoma and required for full migratory capacity of melanoma cells by upregulating CXCL11, an important gene involved in cell migration, revealing the potential functional role of lncRNA BANCR." (PMID 23725405, 2013). "Elevated BANCR expression has been observed in a variety of cancers, including melanoma." (PMID 41463281, 2025). "BANCR knockdown reduces melanoma cell migration by upregulating the chemokine CXCL11." (PMID 40429702, 2025). "BANCR inhibits the expression of miR-204, a suppressor of melanoma cell growth." (PMID 41463281, 2025). "When BANCR was silenced in melanoma cells, levels of miR-204 were decreased." (PMID 37629553, 2023). "Furthermore, a study on colorectal cancer cells found that BANCR works as a miR-203 sponge, while a study on melanoma cells discovered that miR-204 is a direct target of BANCR." (PMID 38137560, 2023). "Interestingly, MEK1/2 or JNK pharmacological inhibition combined with BANCR silencing synergistically affects the proliferative and migration capability of melanoma cells." (PMID 33503876, 2021). "BANCR has been up-regulated in endometrial, gastric, breast, melanoma, and retinoblastoma." (PMID 34409032, 2021). "Moreover, BANCR downregulation significantly decreases melanoma cells proliferation in vitro and tumor size and weight in vivo, mostly via deactivation of ERK and JNK signaling." (PMID 34638331, 2021). "In five different melanoma cell lines, BANCR was found remarkably upregulated compared to controls." (PMID 33572313, 2021).
melanoma (continued). "Moreover, they identified BRAF-regulated lncRNA1 (BANCR), and demonstrated that BANCR knockdown reduced melanoma cell migration, and the effect was rescued by the chemokine CXCL11." (PMID 33198372, 2020). "BANCR is highly expressed in melanoma and promotes melanoma cell migration." (PMID 28009984, 2017). "BANCR promotes melanoma proliferation via activating MAPK pathway." (PMID 28935763, 2017). "BANCR was overexpressed in both melanomas and metastatic samples, which may play an important role in this disease progression." (PMID 29212285, 2017). "BANCR is a 693-bp lncRNA original identified in melanoma cells." (PMID 29383102, 2017). "BANCR was identified as a cancer-promoting long non-coding RNA in melanoma tissues." (PMID 29212285, 2017). "Another study revealed that BANCR expression directly correlates with tumor stage and might contribute to the development of melanoma." (PMID 28350340, 2017). "Knockdown of BANCR inhibited melanoma cell proliferation in vitro and in vivo." (PMID 29212285, 2017). "Their data showed that BANCR promoted melanoma proliferation via modulating ERK1/2 and JNK pathway." (PMID 29212285, 2017). "In conclusion, BANCR can promote melanoma progression via enhancing cell migration." (PMID 29212285, 2017). "In our study, high expression of BANCR was correlated significantly to shortened survival of patients with malignant melanoma, suggesting that BANCR may be a predictor of poor clinical outcome." (PMID 24967732, 2014). "BANCR depletion impaired the migration of the melanoma cells in vitro." (PMID 25289082, 2014). "Taken together, BANCR may be both a new potential target and prognostic factor of malignant melanoma." (PMID 24967732, 2014). "We selected sk-mel-5 cells to perform further assays to test whether BANCR was functionally involved in malignant melanoma tumorigenesis." (PMID 24967732, 2014). "BANCR is overexpressed in melanoma cells and crucial for melanoma cell migration." (PMID 24655544, 2014). "BANCR was involved in melanoma cell proliferation both in vitro and in vivo." (PMID 24967732, 2014). "Although it is reported by a recent study that LINC-PINT is downregulated in melanoma tissues and inhibited cell proliferation through downregulating lncRNA BANCR, whether LINC-PINT has novel functions with diverse mechanism in human melanoma still remains to be identified." (PMID 31921860, 2019). "Furthermore, BANCR expression increased with clinical stages of malignant melanoma." (PMID 28415644, 2017). "In addition, BANCR depletion impairs the migration of melanoma cells in vitro." (PMID 25013510, 2014). "Among the best-characterised pro-angiogenic lncRNAs in melanoma are MALAT1, HOTAIR, BANCR, SLNCR1, and DANCR." (PMID 41463281, 2025). "Thus, targeting BANCR may prevent proliferation and migration of malignant melanoma." (PMID 41463281, 2025). "Other studies identified the role of HOTAIR, MALAT1, BANCR, ANRIL, SPRY‐IT1, SAMMSON, UCA1, and SLNCR1 in melanoma patients and cell lines." (PMID 39764216, 2024). "Several lncRNAs were studied because of the high expression levels in melanoma patients, including SPRY4-IT1, MALAT-1, BANCR, UCA1, HOTAIR, and SNHG8." (PMID 36614156, 2022). "For example, several lncRNAs have been dysregulated in melanoma, including HOTAIR, BANCR, UCA1, and MALAT-1, and related to invasion and metastasis." (PMID 35626352, 2022). "BANCR knockdown, indeed, is able to inhibit melanoma cell migration by upregulating the chemokine CXCL11, and to impair melanoma cell proliferation by modulating ERK1/2 and JNK (MAPK pathway)." (PMID 33503876, 2021). "BANCR is notable, because it is highly upregulated in human primary malignant melanoma and induced by BRAFV600E in comparison to BRAFwt melanoma." (PMID 28350340, 2017). "Several studies have identified known lncRNAs that are abnormally expressed in melanoma, such as SAMMSON, HOTAIR, SLNCR1, BANCR, SPRY4-IT1, ANRIL, Llme23, UCA1, MALATA1, GAS5, H19, CASC15, PTENP1, and MIR31HG." (PMID 28225791, 2017).
melanoma (continued). "Li and colleagues demonstrated that BANCR can activate ERK1/2, its upstream molecule CRAF and JNK in-vitro and in-vivo, which led to proliferation of melanoma cells." (PMID 28350340, 2017). "In contrast to findings implicating BANCR in malignant melanoma, lung cancer, and CRC metastasis, BANCR levels are downregulated in NCI-H1688 and NCI-H446 lung carcinoma (LC) cell lines." (PMID 27686732, 2016). "Overall, the ERV LTR-derived lncRNAs BANCR and SAMMSON, which are specifically expressed in cancer cells, are biomarkers for melanoma and could be potential targets for cancer therapy." (PMID 39408810, 2024). "BRAF-activated non-protein coding RNA (BANCR) was first described as overexpressed in melanoma cells where it is required for melanoma cell migration." (PMID 31003545, 2019). "The linkage between BANCR and MAPK pathway may provide a novel interpretation for the mechanism of proliferation regulation in malignant melanoma." (PMID 24967732, 2014). "The linkage of BANCR and the MAPK pathway may unravel a novel mechanism in the regulation of melanoma proliferation." (PMID 24967732, 2014).